EZH2 (enhancer of zeste 2 polycomb repressive complex 2 subunit)
Diseases named in the same sentence as EZH2 in open-access papers (continued):
Sharing a sentence is not in itself a finding about the gene and the disease.
glioma (continued). "In the current study, we demonstrate that MELK/EZH2/NF-κB signaling, activated in human high-grade gliomas, represents a key functional hallmark of GSCs and results in the poor prognosis of GBM patients." (PMID 31380279, 2019). "Clinically, we observe that the proportion of MELK/EZH2/NF-κB complex is elevated in high-grade gliomas, which is associated with poor prognosis in patients and correlates negatively with survival." (PMID 31380279, 2019). "Gliomas harboring H3K27M mutations have been shown to be more sensitive to EZH2 inhibitors than wildtype H3 gliomas." (PMID 31253791, 2019). "Further, survival analysis was performed to analyze association of MELK/EZH2/NF-κB with prognosis of glioma patients." (PMID 31380279, 2019). "The EZH2/miR-328/β-catenin signaling cascade serves as a novel therapeutic biomarker for glioma, whereas inhibition of EZH2 is also associated with the suppression of glioma growth by restraining the β-catenin signaling pathway." (PMID 31842978, 2019). "We further confirm the association of EZH2 with HOXB13 gene promoter by performing ChIP assays in glioma cells." (PMID 30105866, 2018). "We recently found that elevated EZH2 expression is associated with glioma grade and poorer overall survival." (PMID 29228694, 2017). "Our recent data have shown that increased EZH2 expression was associated with glioma grade, and high expression of EZH2 in GBM (glioblastoma) was determined to be a strong and independent predictor of short overall survival." (PMID 29221202, 2017). "High EZH2 and low miR-524-5p in glioma patients was associated with the longest OS (median OS = 460.6 days; logrank test, P < 0.0001)." (PMID 29221202, 2017). "In order to explore the association of EZH2 with miR-1224-3p, miR-328 and miR-214, their expression profile of miRNA and gene arrays in 158 glioma tissues from CGGA data was analyzed." (PMID 27385092, 2016). "Our recent data have shown that increased EZH2 expression was associated with tumor grade and short overall survival in gliomas." (PMID 27385092, 2016). "Our group has previously reported that the tumor suppressor miR-138 inhibits glioma growth through targeting EZH2 mediated signaling pathway associated with cell proliferation and cell cycle." (PMID 25831237, 2015). "In glioma and renal cell carcinomas, increased EZH2 expression was associated with tumor grade and high expression of EZH2 was determined to be a strong and independent predictor of short overall survival." (PMID 26378043, 2015). "Additional pathways significantly associated with EZH2 expression in glioma were "ATM signaling" (p = 2.2E-6), "G2/M DNA damage checkpoint" (p = 1.0E-5) and "Sonic hedgehog signaling" (p = 1.5E-3)." (PMID 20920292, 2010). "Our analysis suggests that glioma progression is associated with EZH2 overexpression and PRC2 target gene silencing." (PMID 20920292, 2010). "It was reported that by regulating SLC12A5 expression, EZH2 activates the WNK1-OSR1-NKCC1 (lysine-deficient protein kinase-1—oxidative stress responsive 1—NKCC1) pathway to promote glioma migration and tumor invasion, while also promoting SLC12A5 DNA methylation." (PMID 41012498, 2025). "However, a different study identified EZH2 inhibition as a therapeutic target among gliomas harboring H3K27M mutations, which inhibits the PRC2 complex." (PMID 38183103, 2024). "Further, Myc direct transcriptional regulation by EZH2 may establish a new mechanism underlying glioma cancer stem cell maintenance." (PMID 37147437, 2023). "We thus hypothesized that EZH2 expression is involved in H3K27M mutation-induced glioma cell migration and invasion." (PMID 36230759, 2022). "The association between miRNA and EZH2 expression has been investigated in glioma." (PMID 35236381, 2022). "We constructed a risk score that could predict the prognosis of glioma patients by integrating the EZH2 expression with five clinicopathological variables including PRS type, Grade, Chemo status, IDH mutation and 1p19q status." (PMID 33277782, 2021).
glioma (continued). "This signified that EZH2 secretion was linked to glioma malignancy." (PMID 34745848, 2021). "Further, the up- and downregulation of the EZH2 in in vitro as well as in vivo studies may be of a diagnostic as well as therapeutic biomarker in glioma treatment." (PMID 34745848, 2021). "Also, inhibition of EZH2 was linked to the suppression of glioma growth via the inhibition of the β-catenin signaling pathway." (PMID 34745848, 2021). "EZH2 (Enhancer of Zeste 2) belongs to the polycomb transcription factor family of proteins and is associated with various cancer stem cells, including human gliomas." (PMID 22957023, 2012). "Collectively, these data indicate that EZH2 is associated with a malignant phenotype in gliomas." (PMID 23077658, 2012). "In general, EZH2 might be a marker associated with the EMT in glioma." (PMID 36230759, 2022). "Therefore, silencing EZH2 caused decreased proliferation, migration, and invasion of glioma cell." (PMID 36536420, 2022). "Therefore, the potential diagnostic application of EZH2 in distinguishing gliomas from reactive gliosis could be further explored." (PMID 36292072, 2022). "Patients in the high‐EZH2 group had a shorter overall survival time than patients in the low‐EZH2 group, indicating that EZH2 expression may be associated with the survival of glioma patients." (PMID 33277782, 2021). "To further understand the prognostic ability of EZH2 in glioma, we evaluated the association of EZH2 expression with clinicopathologic variables and established a nomogram based on multivariate Cox regression analysis of the 1‐, 3‐ and 5‐year survival of glioma patients." (PMID 33277782, 2021). "The use of EZH2 inhibitors (EZH2is) has been shown to upregulate p16 expression and effectively curb the progression of gliomas." (PMID 40927709, 2025). "Repressive marks such as H3K27me3 and H3K9me3, catalyzed by histone methyltransferases (HMTs) like EZH2, are frequently dysregulated in gliomas and pediatric brain tumors, silencing antigen-processing genes and promoting immune exclusion." (PMID 41341594, 2025). "Single-cell scATAC-seq and scRNA-seq studies reveal glioma stem-like populations enriched in EZH2 and BRD4, alongside exhausted T-cell clusters with stable chromatin scars." (PMID 41341594, 2025). "In particular, EZH2, a histone methyltransferase, is often overexpressed in gliomas, where it promotes tumorigenesis by silencing tumour suppressor genes and disrupting normal astrocyte differentiation." (PMID 40022506, 2025). "Enhancer of zeste homolog 2 (EZH2), a pivotal histone methyltransferase in the PRC2, undergoes alterations in gliomas that lead to both gain- and loss-of-function mutations." (PMID 40927709, 2025). "Another group showed that HDACi and tazemetostat, an Enhancer of Zeste 2 (EZH2) inhibitor, synergize against a murine model of IDHmut glioma." (PMID 41066183, 2025). "EZH2 is a downstream target of Myc and acts to expand the tumor stem cell pool in glioma, breast cancer, and prostate cancer and to promote proliferation, migration, and invasion in GBM." (PMID 40563634, 2025). "This study provides novel insights into the molecular pathways governing astrocyte differentiation and suggests EZH2 as a promising therapeutic target for gliomas and other CNS disorders." (PMID 40022506, 2025). "For instance, B7-H4 and EZH2 have been shown to limit CD8 + T cell infiltration in glioma and esophageal squamous cell carcinoma, respectively, providing new potential therapeutic targets." (PMID 41444923, 2025). "In a previous study, high-grade astrocytic glioma exhibited higher EZH2 expression than low-grade glioma or normal brain tissue." (PMID 39636550, 2025).
glioma (continued). "By targeting these promoters, HOXDeRNA evicts the Polycomb repressive complex 2 (PRC2), specifically displacing EZH2, thereby releasing key glioma driver genes from epigenetic silencing." (PMID 41154382, 2025). "EZH2 serves as a crucial intermediary regulatory factor that enhances the proliferation, migration, and invasion of glioma cells." (PMID 39043634, 2024). "Another study highlighted the role of enhancer of zeste homolog 2 (EZH2) in controlling antitumor immunity in glioma." (PMID 39487556, 2024). "Our study again confirms the abnormal overexpression of EZH2 in gliomas, significantly correlated with patient prognosis." (PMID 38886655, 2024). "miR-133b-containing MSC-Exos blocked glioma cell invasion, migration, and proliferation by inhibiting EZH2 and the Wnt/β-catenin signaling pathway." (PMID 39450275, 2024). "Glioma is the most common malignant tumor of the central nervous system, with EZH2 playing a crucial regulatory role." (PMID 38886655, 2024). "In vivo, IHMT-337 inhibits glioma growth in a mouse model, accompanied by EZH2 degradation and KCC2 expression restoration." (PMID 38886655, 2024). "Recent reports indicate that the high expression of EZH2 in gliomas is attributed to HCMV infection, and successful induction of GBM was achieved in vitro models by transplanting HCMV-infected astrocytes." (PMID 38886655, 2024). "ANCR can enhance the invasion and migration of glioma cells by interacting with EZH2 and regulating PTEN expression." (PMID 38967893, 2024). "Studies propose that EZH2 can enhance glioma resistance to temozolomide (TMZ) by regulating the FADD/PARP1 axis." (PMID 39069522, 2024). "Further experiments have substantiated the regulation of glioma pyroptosis by EZH2 through STAT3 inhibition (SH-4–54) and recovery (RO8191)." (PMID 39069522, 2024). "Our research confirms significantly elevated EZH2 expression in gliomas, correlating with patient prognosis." (PMID 38886655, 2024). "Building upon the findings above, we aimed to inhibit the activation of the WNK1-OSR1-NKCC1 cascade and, consequently, glioma migration at its source using an EZH2 inhibitor." (PMID 38886655, 2024). "EZH2 is a protein significantly upregulated in gliomas and can promote malignant progression through various mechanisms." (PMID 38886655, 2024). "Another epigenetic regulator relevant to HGG is the methyltransferase, EZH2, which is overexpressed in gliomas and correlated with high-grade gliomas." (PMID 38183103, 2024). "Subsequently, we investigated the ability of different concentrations of IHMT-337 to degrade EZH2 in glioma cells." (PMID 38886655, 2024). "The use of the EZH2 inhibitor DZNep not only inhibits the occurrence and development of glioma but also activates glioma pyroptosis." (PMID 39069522, 2024). "Studies have examined the role of EZH2 in apoptosis, autophagy, and cell cycle regulation in gliomas." (PMID 39069522, 2024). "We then evaluated the effect of IHMT-337 on glioma cell migration, revealing a significant inhibition of cell migration promoted by EZH2 overexpression, as well as the suppression of cell migration induced by KCC2 downregulation." (PMID 38886655, 2024). "The glioma cells harboring the IDH1R132H mutation were resistant to Panobinostat, but this is rectified by EZH2 inhibition." (PMID 38334611, 2024). "This study further explores the abnormal expression of EZH2 and its mechanisms in regulating glioma progression." (PMID 38886655, 2024). "EZH2 facilitates glioma proliferation, migration, and invasion alongside promoting SLC12A5 DNA methylation." (PMID 38886655, 2024). "EZH2 often plays a role as a cancer promoter in gliomas, primarily regulating gene expression at the epigenetic level by catalyzing trimethylation of lysine 27 on histone H3 (H3K27me3)." (PMID 39069522, 2024). "We validated the abnormally high expression of EZH2 in gliomas, which promotes proliferation, migration, and invasion of glioma cells." (PMID 38886655, 2024).
glioma (continued). "Studies have demonstrated that reducing EZH2 levels can decrease the invasive, migratory, and proliferative abilities of glioma cells, while also promoting apoptotic processes." (PMID 39043634, 2024). "EZH2 exerts its influence on gliomas through methylation and involvement in multiple signaling pathways that regulate glioma development." (PMID 39069522, 2024). "EZH2's involvement in different glioma development stages suggests its potential as a new therapeutic target for improving patient prognosis." (PMID 38886655, 2024). "EZH2's structure is conducive to phosphorylation and O-GlcNAcylation, influencing glioma cell invasion and metastasis." (PMID 39487556, 2024). "Both tumor-derived glioma cells and transformed OPCs show similar responses to EZH2 and HDAC inhibition, suggesting that this mechanism is retained throughout the process of OPC gliomagenesis." (PMID 38334611, 2024). "For instance, EZH2 affects the downstream molecule NF-κB through methylation, enhancing transcriptional activity and promoting self-renewal of glioma stem-like cells." (PMID 39043634, 2024). "EZH2 inhibitors (EZH2is) enhance p16 tumor suppressor gene expression, affecting glioma progression." (PMID 36647827, 2023). "Taken together, these results indicate that SPRY4‐IT1 sponges miR‐101‐3p to induce EZH2‐mediated cell proliferation and angiogenesis in glioma cells." (PMID 36479622, 2023). "In glioma, some synthetic compounds have been found to induce the G1 phase arrest of tumor cells by inhibiting EZH2 expression and reducing the inhibitory effect of PRC2 on p21, p27, and p16 gene expression." (PMID 38264522, 2023). "EZH2 was shown to expand the stem cell pool and the tumor-initiating cells in glioma, breast and prostate cancer, hence enhancing accelerated initiation, metastasis and growth." (PMID 37147437, 2023). "Propofol promotes glioma growth through zDHHC5 and EZH2, and tight control of Propofol dosage in the clinic leads to better prognosis for patients after surgical removal of tumors." (PMID 38293675, 2023). "A preclinical study demonstrated that EZH2 expression is significantly upregulated in the U87 and U251 glioma cells compared to HA-1800 human astrocytes." (PMID 37887005, 2023). "A total of 57.1% (32/56) glioma specimens with high NFAT5 K668 methylation levels displayed enhanced protein expression of EZH2 pS21." (PMID 37429858, 2023). "The aberrant expression of EZH2 impacts gene expression by binding to promoter regions and affecting methylation status, playing an oncogenic role in glioma." (PMID 36647827, 2023). "We further elucidated that SPRY4‐IT1 promotes glioma cell proliferation and angiogenesis in vitro and in vivo, and activates the miR‐101‐3p/EZH2/VEGFA pathway." (PMID 36479622, 2023). "Mechanistically, SPRY4‐IT1 upregulated EZH2 expression by sponging miR‐101‐3p to induce VEGFA expression in glioma cells." (PMID 36479622, 2023). "Rescue experiments further confirmed that SPRY4‐IT1 promoted glioma cell proliferation and angiogenesis via the miR‐101‐3p/EZH2/VEGFA signaling axis." (PMID 36479622, 2023). "Enhancer of zeste homolog 2 (EZH2) is a histone methyltransferase subunit of PCR2 that is altered in gliomas." (PMID 36647827, 2023). "Collectively, these data indicated that SPRY4‐IT1 promoted glioma cell proliferation and angiogenesis via the miR‐101‐3p/EZH2 axis by mediating VEGFA downregulation." (PMID 36479622, 2023). "Our in vivo results suggest a potential application of CA to synergize the glioma-suppressive effects of EZH2 inhibitors." (PMID 38264522, 2023). "In fact, low expression of TUG1 lncRNA and high expression of Enhancer of zeste homolog 2 (EZH2) was observed in glioma cells." (PMID 37958880, 2023).
glioma (continued). "High EZH2 expression served as an independent predictor of poor 5-year OS in gliomas, with a hazard ratio of 3.824 (95% confidence interval 1.357–10.779, p = 0.011)." (PMID 36292072, 2022). "In IDH1 R132H-negative gliomas, there was a trend toward shorter 5-year PFS (mean = 8.0 months, p = 0.001) and 5-year OS (mean = 28.7 months, p = 0.06) in gliomas demonstrating high EZH2 expression compared with those with low EZH2 expression." (PMID 36292072, 2022). "High EZH2 immunoexpression is an unfavourable independent prognostic predictor of poor survival in gliomas." (PMID 36292072, 2022). "To better uncover the relationship between EZH2 and p65 in the progression of human glioma, we further examined EZH2 and p65 expression in human glioma samples (n=180) by immunohistochemical (IHC) staining." (PMID 36263173, 2022). "Recent studies have also shown that EZH2 is a potential therapeutic target for H3K27M-mutant pediatric gliomas." (PMID 36230759, 2022). "This study aimed to investigate EZH2 immunoexpression in glioma patients and explore its clinical significance in tumour progression in relation to IDH1 R132H protein mutant status." (PMID 36292072, 2022). "Enhancing miRNA-32 expression significantly impairs proliferation and migration of glioma cells via EZH2 down-regulation." (PMID 35236381, 2022). "EZH2 inhibition decreased glioma cell proliferation in vitro and increased the survival of mice with H3F3AK27M-mutated gliomas." (PMID 36142368, 2022). "Binding of another lncRNA HOTAIR to EZH2 of the polycomb repressive complex (PRC) 2 leads to transcriptional silencing of tumor suppressor genes in glioma." (PMID 36009578, 2022). "In gliomas, miR-1224-3p was inhibited by EZH2, which in turn regulated β-catenin expression through binding to its 3′UTR, thus controlling proliferation, invasion, and glucose metabolism of cells." (PMID 35494023, 2022). "Accumulating data indicates that enhancer of zeste homology 2 (EZH2) and isocitrate dehydrogenase 1 (IDH1) are implicated in promoting tumourigenesis in a myriad of malignancies including gliomas." (PMID 36292072, 2022). "We aimed to determine the immunoexpression of EZH2 in gliomas and its correlation with clinicopathological variables." (PMID 36292072, 2022). "Several previous studies investigated the prognostic role of EZH2 in glioma patients; however, the results remained controversial." (PMID 36292072, 2022). "In the current study, we described the correlation of EZH2 with IDH1 R132H protein mutant status in various grades of gliomas." (PMID 36292072, 2022). "This further supported the previous claim that EZH2 plays a pivotal role in glioma development and progression." (PMID 36292072, 2022). "Another study found that mesenchymal stem cell-derived exosomal miRNA-133b suppressed glioma progression via the Wnt/β-catenin signaling pathway by targeting EZH2." (PMID 36438184, 2022). "It has also been reported that EZH2 can protect glioma stem cells from radiation-induced cell death." (PMID 36071871, 2022). "Semiquantitative scoring of the western blot analysis indicated that EZH2-92aa was preferentially expressed in tumour tissues in our in-house cohort of 63 high-grade glioma samples." (PMID 35970825, 2022). "High EZH2 expression was found to be a helpful indicator for supporting the diagnosis of a high-grade glioma." (PMID 36292072, 2022). "TTBK2 was found to modulate the cell proliferation and invasion in glioma cell lines via miR-520b/EZH2 axis." (PMID 35685372, 2022). "When GSK126, a specific EZH2 inhibitor, was used to treat glioma cells, the overall level of H3K27me3 in glioma cells was effectively decreased." (PMID 36527092, 2022). "Other regulatory factors modulated miR-1224-3p expression in gliomas, such as EZH2 and MIR44435‐2HG (lncRNA MIR4435‐2 Host Gene)." (PMID 35494023, 2022).